IL6 (interleukin 6)
Diseases named in the same sentence as IL6 in open-access papers (continued):
Sharing a sentence is not in itself a finding about the gene and the disease.
cancer (continued). "IL-6 is a multifunctional cytokine implicated in both innate and acquired immune responses, hematopoiesis, inflammation as well as in the regulation of growth and differentiation of cancer cells." (PMID 26338965, 2015). "Based on these observations, we thereby develop a completing hypothesis that the association between circulating IL-6 and cancer is causally related." (PMID 26096712, 2015). "They observed that patients with high levels of IL-6 showed >5% weight loss after 6 months, suggesting that IL-6 could be responsible for the induction and maintenance of cancer cachexia." (PMID 26508818, 2015). "IL-6 and IL-8 are interleukins linked to increased cancer invasion and migration." (PMID 26000019, 2015). "In this meta-analysis of 80 qualified articles, we employed Mendelian randomization to test the completing hypothesis that the association between circulating IL-6 and cancer is causal." (PMID 26096712, 2015). "However in Asians, this association was totally reversed with 1 pg/mL reduced circulating IL-6 corresponding to an 17% increased cancer risk (95% CI: 1.03 to 1.68)." (PMID 26096712, 2015). "Similarly, IL-6 is also an inflammation-associated pleiotropic cytokine, which can be secreted by a wide array of immune, endothelial as well as cancer cells in an inducible manner." (PMID 25868978, 2015). "In addition, several studies have shown that high IL-6 serum levels are associated with progression of cancer and the metastasis of cancer cells." (PMID 26148092, 2015). "Serum IL-6 level fluctuation was determined using an immunological technique, before detecting its possible association with the subjects’ age, gender, drinking and smoking history, cancer site, and disease severity." (PMID 26082902, 2015). "This is the principal limitation of this Mendelian randomization meta-analysis, that is, if the other flanking variants within or near IL-6 gene related to cancer risk are in linkage disequilibrium with -174G/C variant we have examined, this will confound our findings." (PMID 26096712, 2015). "Among other cell types, cancer-associated fibroblasts (CAF) stained positive for IL6." (PMID 26215971, 2015). "In cancer patients, high levels of IL-6 and IL-8 are associated with poor outcome." (PMID 26932376, 2014). "Elevated systemic levels of IL-6 have been associated with muscle wasting in cancer and aging." (PMID 24906706, 2014). "We investigated the results that suggest that induction of TLR8 by 3M002 in CRC cancer cell lines can reduce the secretion of IL-6 and IL-8, however, the cellular mechanisms associated with the inhibition of metastasis particularly driven by 3M002 remain to be elucidated." (PMID 25547486, 2014). "Additionally, a direct causal link between cancer and inflammation is given by the association of let-7, IL6, and NFκB, which are major players involved in the epigenetic switch from inflammation to cell transformation." (PMID 25276782, 2014). "Importantly, STAT3 is prominently activated at sites of chronic inflammation by IL-6 and initiates a positive that is highly predisposing condition for cancer." (PMID 25238263, 2014). "Muscle STAT3 activation by IL-6 is a common feature of cancer-associated muscle wasting." (PMID 24787299, 2014). "Second, excessive sitting time could increase levels of inflammatory factors such as tumor necrosis factor-α, interleukin-6, and leptin which are known risk predictors for cancer." (PMID 25153314, 2014). "The overexpression of let-7 via the transfection of let-7 precursors decreased IL-6 expression and repressed the adipogenic potential and metastasis-promoting activity of cancer-associated MSCs, which was consistent with the inhibition of IL-6 3′UTR luciferase activity." (PMID 23977098, 2013). "The role of IL-6 in the enhanced adipogenesis of cancer-associated MSCs was also assessed." (PMID 23977098, 2013).
cancer (continued). "Interleukin (IL-6) is a proinflammatory cytokine whose irregular production has been implicated in the development of various inflammatory and autoimmune diseases including cancer." (PMID 24202339, 2013). "Several studies have assessed interleukin-6 (IL-6), a multifunctional cytokine that participates in the inflammatory and immune responses and has been shown to promote the growth of cancer cells as well as associated with an increased rate of metastasis and an altered immune status." (PMID 24376459, 2013). "Thus, IL-6 production from EGFR-TKI-treated cancer cells increases the risk of chemoresistance and acute interstitial pneumonia." (PMID 23592411, 2013). "The IL-6/JAK/STAT pathway is a key signal transduction pathway implicated in the pathogenesis of many human cancers, suggesting that kinase inhibitors targeting JAK/STAT3 may have a broad spectrum of antitumor activity." (PMID 23531921, 2013). "We, therefore, investigated whether the overexpression of IL-6 by cancer-associated MSCs occurs through the regulation of miRNAs." (PMID 23977098, 2013). "In terms of disease states, overexpression of IL-6 can cause cancer cachexia." (PMID 22716658, 2012). "In addition, IL6 gene polymorphisms are associated with increased cancer risk for colorectal carcinoma." (PMID 23185547, 2012). "Moreover, a quantitative meta-analysis concluded that fatigue is associated with elevations in circulating levels of IL-6 in cancer patients." (PMID 22708709, 2012). "Several studies have shown a link between polymorphisms in IL–1β, IL–6, IL–10 and cancer risk." (PMID 22567049, 2011). "IL-6 signaling pathways in epithelial cancer cells have also been linked to in vivo aggressiveness by affecting epithelial-to-mesenchymal conversion or conferring the cancer stem cell-like properties of these cells." (PMID 21967801, 2011). "Both CCL2 and IL-6 have been implicated in the process of cancer metastasis." (PMID 21826248, 2011). "Furthermore, IL-6 and its downstream signaling pathway have been implicated in the regulation of proliferation, survival, and metabolism of cancer cells." (PMID 20637104, 2010). "High expression of IL6 also is associated with malignant tumors and deep vein thrombosis disease." (PMID 20003295, 2009). "Moreover, Cox-2 dependent expression of IL-6 has been implicated in STAT3 activation and IL-6-dependent STAT3 activation has been shown to increase angiogenesis in several cancers." (PMID 19523218, 2009). "Alternatively, development of anti-IL-6 or anti-IL-6 receptor monoclonal antibodies could be beneficial for future adjuvant immune therapy for cancer patients with genetic predisposition for IL-6 overexpression." (PMID 18205904, 2008). "Longer LOS was associated with cancer, transferrin, IL-6 and albumin (p < 0.05)." (PMID 17505683, 2007). "In a study of outcomes from thoracic surgery, Shaw and colleagues genotyped six polymorphisms in five genes, finding associations for SNPs in tumor necrosis factor (TNF) and interleukin-6 (IL6) with the risk of complications in 155 patients undergoing lung resections for cancer." (PMID 17686149, 2007). "Interestingly, in the colon-26 murine model of cancer cachexia associated with systemic inflammation there appears to be a complex intratumoural amplification loop between IL-1β and IL-6, which can be downregulated by IL-10." (PMID 17088911, 2006). "Furthermore, neither sIL-6R nor sgp130 concentrations were significantly associated with either IL-6 or C-reactive protein concentrations in the cancer patients." (PMID 15570310, 2004). "In conclusion, this study provides further evidence that IL-6 may be pivotal in haemostasis and angiogenesis associated with cancer." (PMID 12454774, 2002). "This review outlines the clinical relevance of IL-6 as a potential prognostic biomarker and describes its mechanistic involvement in the development of castration resistance, with emphasis on its interplay with distinct cancer-associated fibroblast (CAF) subtypes." (PMID 41660621, 2026).
cancer (continued). "Another study based on 164 pre-treatment Asian CRC patients also found that elevated IL-6 levels in patients may be associated with a higher risk of early cancer progression in CRC, indicating that IL-6 levels may act as an important predictor for CRC progression and poor prognosis." (PMID 39980561, 2025). "Moreover, probiotic-derived metabolites such as indole derivatives and polyamines modulate inflammatory signaling by inhibiting NF-κB and reducing the production of pro-inflammatory cytokines like IL-6 and IL-1β, which are often elevated in cancer-associated inflammation." (PMID 40290037, 2025). "Notably, the combination of IL-6 < 185 pg/mL and IL-10 < 20 pg/mL identified low-risk patients with a septic shock rate of only 0.7%, suggesting clinical utility for risk stratification in febrile pediatric cancer patients." (PMID 40647525, 2025). "Although PCT showed stronger association with septic shock (RR = 2.24, p = 0.001), IL-6 (RR = 8.21) and IL-10 (RR = 4.28) demonstrated superior predictive capacity for this critical outcome, emphasizing the clinical utility of cytokine-based risk stratification in febrile pediatric cancer patients." (PMID 40647525, 2025). "Regular exercise may also suppress cancer-associated cachexia driven by IL-6 signaling." (PMID 40895542, 2025). "IL-6 has been implicated in tumourigenesis by promoting cell proliferation, angiogenesis and resistance to apoptosis in several cancers, including CC, and is now considered a critical biomarker and therapeutic target in various diseases, particularly in inflammation-related pathologies and cancer." (PMID 41561529, 2025). "Furthermore, hub genes like EGFR and IL6, already implicated in other cancers, may also represent druggable targets in VS that warrant further validation." (PMID 41231782, 2025). "Moreover, cancer-associated fibrosis is marked by chronic inflammation within cyto/chemokines (i.e., IL-6, IL-8, IL-17A, and IL-1α), and growth factors (i.e., SDF-1, HGF, PDGF, and TGF-β) are released by both malignant and non-cancer cells, contributing to tumor cell proliferation and invasion." (PMID 40649899, 2025). "In cancer studies, comprehensive pathway analysis shows that PANoptosis score positively correlates with several pathways associated with immune and inflammatory responses in pan-cancer, including IL6-JAK-STAT3 signaling, the interferon-gamma (IFN-γ) response, and IL2-STAT5 signaling." (PMID 38169587, 2024). "Moreover, S. mutans infections in the oral cavity are associated with chronic inflammation, IL-6 production, and epithelial transformation, which may cause cancer development and locally advanced disease stages." (PMID 38396998, 2024). "Thus, the neo-structure, inducing pathological IL-6 production, associated with a reduced survival of cancer patients, can be selectively removed by the therapeutic administration of antibodies leaving the function of IL-6 needed for the normal activity of the immune system intact." (PMID 39518029, 2024). "While it is true that elevated levels of IL-6 may be associated with a worse prognosis in cancer patients, this can also reflect the production of IL-6 in response to the physiologic effects of having advanced cancer, whereby the acute phase response is induced." (PMID 38611065, 2024). "The analysis of 23 real samples of genomic DNA voluntarily collected from 6 controls and 17 cancer patients revealed that the bioassay can differentiate between the controls having the major allele and the patients which have one or two point mutations in one or two alleles of the IL6 gene." (PMID 36832006, 2023). "Moreover, TLR signaling by invading pathogens or during cancer-associated inflammation, activate Rac1 and Cdc42 which leads to Nuclear Factor kB (NFκB) transcriptional activity and secretion of inflammatory cytokines such as interleukin-6 (IL-6)." (PMID 37397366, 2023).
cancer (continued). "Additionally, IL-6 subsidizes a variability of disease states, including many types of cancer development, and metastasis, progression, and increased levels of IL-6 are associated with a higher risk of cancer and can also serve as a prognostic marker for cancer." (PMID 37754068, 2023). "Importantly, an inflammatory environment promoted by cancer may lead to the activation of the interleukin 6 signaling pathway, and this can cause metastases." (PMID 37958980, 2023). "Furthermore, elevated IL-6 is associated with a worse prognosis in several cancers." (PMID 38022653, 2023). "Interestingly, recent studies reported that coexistent PIK3CA/ARID1A mutations in OCCC are responsible for high levels of IL-6 and this mechanism may promote cancer growth and as such, could represent a potential therapeutic target in OCCC." (PMID 38164130, 2023). "Both IL-6 and IL-8 have been implicated in the pathogenesis and progression of several solid tumor types, including breast, prostate, colon, and pancreatic cancers, and indeed elevated expression of both molecules has been associated with increased cancer aggressiveness and metastatic burden." (PMID 38187701, 2023). "Furthermore, CD14CTX express certain molecules associated with immunosuppression such as CXCL8, TGFB1, and IL6, which could be targeted by anti-cancer therapy independently." (PMID 36130508, 2022). "Several hormones and cytokines, such as leptin, ghrelin, interleukin (IL)-1β, IL-6, and tumor necrosis factor alpha, contribute to the inflammation-mediated loss of fat and muscle and actively participate in the homeostasis of muscle and fat tissues in patients with cancer." (PMID 35203597, 2022). "Interestingly, it has been shown that IL-6 can be secreted both by cancer and stromal cells like cancer associated fibroblasts (CAFs), TAMs, and endothelial cells in various cancers and induces proliferation, angiogenesis and metastasis by activating STAT-3 pathway." (PMID 35300689, 2022). "Promoters of cellular growth, such as Fibroblast activation protein (FAP), cancer-associated fibroblasts (CAFs), and fibronectin, induce the activation of the mechanistic target of rapamycin (mTOR) and the secretion of cytokines, such as IL6 and CXCL12, which recruit T-cells CD4+." (PMID 35743107, 2022). "Moreover, the IL-6/STAT3/PTEN/NF-κB inflammatory axis is preferentially activated in CD44+CD24− stem-like breast cancer cells compared with other tumor cell types such as cancer associated fibroblasts and inflammatory cells." (PMID 39086963, 2022). "CRC liver metastasis is supported by cancer-associated fibroblasts which are recruited from pericryptal and distant fibroblast precursors to produce a prometastatic microenvironment through inflammatory activation of IL-6 and the monocyte chemo-attractant protein-1 (MCP-1)." (PMID 35954156, 2022). "Therefore, blocking IL-6 or inhibiting its associated signaling alone or in combination with conventional anti-cancer therapies could be a potential therapeutic strategy in various cancers." (PMID 36015338, 2022). "IL-6 may be associated with muscle wasting in animal models of cancer cachexia." (PMID 36358681, 2022). "However, it is notable that blood IL-6 is weakly associated with pan-cancer risk." (PMID 35359426, 2022). "Additionally, cancer-related inflammation is regarded as a hallmark of the disease, and some inflammatory factors can have a profound role in the development of the disease, particularly IL-6." (PMID 36153540, 2022). "In addition, several studies confirmed that the high expression of the inflammatory factor IL-6 was associated with the disease progression in patients with NB and helped the cancer cells to escape the killing of drugs, which was one of the indicators of poor prognosis." (PMID 35535346, 2022). "Therefore, inhibition of CAF-CCA interaction could be considered as a potent therapeutic approach for cancers associated with IL-6/STAT3 activation." (PMID 36091805, 2022).
cancer (continued). "IL-6 is a multifunctional cytokine that is recently known to be an important constituent of cancer-associated cytokine complex which ultimately results in a systemic immune stimulation together with cancer-induced immune suppression that eventually protects the cancer cells." (PMID 33906302, 2021). "Certain inflammatory cytokines, such as IL-6 and IL-17, are diagnostic markers for early phase of inflammation and they interact in the promotion of tumors and cancer progression and they act in the regulation of Cu uptake mechanisms, thus contributing to the accumulation of Cu in cancer cells." (PMID 34568365, 2021). "Thus, skin colonization with IL-6-inducing S. aureus may cause a persistent accumulation of lingering immune cells, which has been linked to cancer progression." (PMID 35145494, 2021). "The categorization of cancer groups into three risk groups may bias the outcome in the current study by introducing misclassification of the actual risk of primary cancer diagnosis and association with IL-6 and YKL-40." (PMID 34200156, 2021). "Interestingly, human cachectogenic cancers are commonly associated with the ability to induce systemic autophagy through the secretion of proinflammatory cytokine IL-6; hence, research efforts should focus on the autophagic effect of these molecules in distant tissues." (PMID 34831432, 2021). "Particularly, they reported significant association of IL-6 gene with 2 types of cancer risks (liver and prostate) and insignificant association with 7 types of cancer risks (breast, cervical, colorectal, gastric, lung, lymphoma and myeloma) by the sub-group analysis of cancer types." (PMID 33684135, 2021). "The GG genotype of the IL-6 rs1800795 polymorphism and the AA genotype of rs4073 IL-8 were associated with a poor clinical prognosis, which may indicate that patients with these genotypes have a potential risk of developing highly malignant tumors." (PMID 33573284, 2021). "Therefore, we focused on investigating whether IL-6, which is associated with muscle atrophy and cancer cells." (PMID 34863141, 2021). "TGF-β, IL-8, TNF-α and IL-6, Colony-stimulating factor (CSF)-1, IFNs cause an alteration in Treg cell diffraction and stimulate a Treg-mediated increased expression of PD-L-1, inhibiting the anti-tumour effect of cancer-effector cells and promoting cancer immune escape." (PMID 34885253, 2021). "Furthermore, the Hb level was inversely correlated with interleukin-6 expression, oxidative stress markers, and C-reactive protein level among patients with advanced cancer, which implied that inflammatory status is associated with worse iron metabolism in advanced cancers." (PMID 34034691, 2021). "The in vitro rhLf-mediated inhibition of cancer proliferation was associated to up-regulation of NF-kβ signaling as well as to the down-regulation of pro-inflammatory and pro-metastatic cytokines, including IL-8, IL-6, granulocyte macrophage colony-stimulating factor and TNF-α." (PMID 32183434, 2020). "Furthermore, High IL-6 expression is associated with poor prognosis in a variety of cancers." (PMID 31249807, 2019). "Therefore, it was reasonable to assume that inflammation associated cancer might also be driven by IL-6 trans-signaling." (PMID 31694340, 2019). "However, the downstream effectors of the IL-6/STAT3 signaling axis that underlie cancer stem cell (CSC) properties are yet unknown." (PMID 30804456, 2019). "Importantly, these alterations were not due to the reduced food intake and were partially counteracted by the anti-IL-6 treatment, suggesting that, as for the gut barrier function, cancer cells and associated increased IL-6 levels contribute to the gut microbial dysbiosis." (PMID 29719601, 2018). "Therefore, mastectomy increases IL-6 in cancer-associated adipocytes." (PMID 29777144, 2018).